P4HA1 (prolyl 4-hydroxylase subunit alpha 1)
Diseases named in the same sentence as P4HA1 in open-access papers (continued):
Sharing a sentence is not in itself a finding about the gene and the disease.
triple-negative breast carcinoma (5 papers, 2018 to 2025). An invasive breast carcinoma which is negative for expression of estrogen receptor (ER), progesterone receptor (PR), and human epidermal growth factor receptor 2 (HER2). "P4HA1 is frequently upregulated in cancer, particularly in triple-negative breast cancer (TNBC), a subtype associated with poor prognosis and aggressive growth." (PMID 40694594, 2025). "P4HA1 is frequently upregulated in highly aggressive triple-negative breast cancer, and has been implicated in tumor progression, metastasis, and chemoresistance." (PMID 40694594, 2025). "The absence of the pro-inflammatory subcluster of basal epithelial cells in P4HA1-deficient 6Ho mice suggests that P4HA1 plays a key role in regulating pro-inflammatory responses in these cells and may serve as a potential therapeutic target for triple-negative breast cancer treatment." (PMID 40694594, 2025). "Early study had shown that inhibiting P4HA1 increased chemosensitivity in triple-negative breast cancer." (PMID 34659558, 2021). "We and others showed previously that knocking down P4HA1 inhibited invasive branching in triple-negative breast cancer cells but had very little effect on cell proliferation." (PMID 32927660, 2020). "Previous studies have shown that inhibiting P4HA1 could make triple-negative breast cancer sensitive to chemotherapy." (PMID 34659558, 2021). "In triple-negative breast cancer, P4HA1 expression was induced and correlated with short relapse-free survival whether or not patients had received chemotherapy." (PMID 32166002, 2020).
breast tumor (4 papers, 2021 to 2024). "P4HA1 is associated with cellular α-KG and succinate levels in breast tumor cells." (PMID 38238754, 2024). "In the Curtis data set, the P4HA1 mRNA rate was significantly higher in the breast tumor (FC = −1.570, p = 4.72E-5)." (PMID 33692831, 2021). "In addition, they described that HIF-1α plays a critical role in collagen biogenesis in breast tumors by upregulating the expression of P4HA1, P4HA2, PLOD1, and PLOD2 hydroxylases as well as the lysyl oxidase family members LOX, LOXL2, and LOXL4." (PMID 37686617, 2023).
Myocardial fibrosis (4 papers, 2021 to 2025). "Specifically, authors showed that liraglutide was able to reduce myocardial fibrosis, acting on cardiac fibroblasts exposed to high glucose, targeting P4HA1 expression." (PMID 39828692, 2025). "Downregulation of P4HA1 is involved in liraglutide-mitigated myocardial fibrosis through the CD36-JNK-AP1 pathway." (PMID 33981730, 2021).
nasopharyngeal carcinoma (4 papers, 2024 to 2025). A carcinoma arising from the nasopharyngeal epithelium. "Moreover, we confirmed that P4HA1 was associated with poor prognosis in nasopharyngeal carcinoma and could promote proliferation and metastasis in nasopharyngeal carcinoma." (PMID 38806556, 2024). "P4HA1 promotes nasopharyngeal carcinoma progression by activating HMGCS1, which inhibits erastin-induced ferroptosis and supports the proliferation and survival of both adherent and ECM-detached tumor cells." (PMID 40959429, 2025). "Transwell assay results showed that P4HA1 played an important role in promoting metastasis of nasopharyngeal carcinoma cells." (PMID 38806556, 2024). "Based on our results, we concluded that P4HA1 is a pro-oncogene that is highly expressed in nasopharyngeal carcinoma and plays an important role in mediating cell proliferation and metastasis." (PMID 38806556, 2024). "First, we used immunohistochemistry to verify the expression of P4HA1 in clinicopathologic specimens of nasopharyngeal carcinoma." (PMID 38806556, 2024). "We divided 52 clinical pathological samples of nasopharyngeal carcinoma into P4HA1 high expression group and P4HA1 low expression group." (PMID 38806556, 2024). "Correlation experiments also confirmed that P4HA1 can promote the proliferation and metastasis of nasopharyngeal carcinoma." (PMID 38806556, 2024). "Immunohistochemistry analysis revealed that P4HA1 was highly expressed in nasopharyngeal carcinoma tissues, which is consistent with bioinformatics analysis results." (PMID 38806556, 2024). "CCK-8 and colony formation assays showed that P4HA1 could promote the proliferation of nasopharyngeal carcinoma cells." (PMID 38806556, 2024). "Correlation experiments confirmed that P4HA1 may serve as a prognosis biomarker and plays a role in the progression of nasopharyngeal carcinoma." (PMID 38806556, 2024). "Moreover, P4HA1 can also activate HMGCS1 to promote nasopharyngeal carcinoma progression." (PMID 41469036, 2025).
osteosarcoma (4 papers, 2021 to 2023). A usually aggressive malignant bone-forming mesenchymal neoplasm, predominantly affecting adolescents and young adults. "P4HA1 has also been reported to be closely associated with the regulation of hypoxic microenvironment and immune infiltration in osteosarcoma." (PMID 37055822, 2023). "Finally, we chose P4HA1 as a representative gene to verify the function of risk genes in vitro and in vivo and found that P4HA1 could promote the metastasis of osteosarcoma cells." (PMID 33952718, 2021). "The knockdown of MYC and P4HA1 significantly inhibited the proliferation, invasion and migration of osteosarcoma cells." (PMID 37055822, 2023). "Second, the specific mechanisms of DCN and P4HA1 in osteosarcoma were still unclear." (PMID 33816483, 2021). "Although there were no available antibodies to TAC4, the protein expression of MYC, P4HA1, and RAMP1 was found to be significantly higher in osteosarcoma tissues than in normal tissues." (PMID 37055822, 2023). "In this study, we explored the role of four genes (EFNA1, P4HA1, STC2, and MAFF) profiled in a previous study on osteosarcoma." (PMID 34337075, 2021). "In addition, in the independent validation cohort, it was found that osteosarcoma patients with high MYC, P4HA1, and RAMP1 protein expression had worse RFS." (PMID 37055822, 2023). "We examined 198 glycolysis-related genes that showed differential expression in metastatic and non-metastatic osteosarcoma samples in the TARGET database, and identified three genes (P4HA1, ABCB6, and STC2) for the establishment of a risk signature." (PMID 33952718, 2021).
prostate adenocarcinoma (4 papers, 2014 to 2023). "Cancer type details of overexpressed genes indicated that ANGPLT4, P4HA1, and VEGFA were mostly mutated in prostate adenocarcinoma and prostate neuroendocrine carcinoma." (PMID 37048688, 2023). "We conducted Oncomine Platform (Life Technologies, Ann Arbor, MI) database analyses on publicly available microarray datasets and found that P4HA1 is over-expressed in prostate adenocarcinoma (p=8.57E-4) and metastatic samples (p=2.22E-7) compared with normal tissues." (PMID 25115393, 2014).
esophageal cancer (3 papers, 2022 to 2024). A primary or metastatic malignant neoplasm involving the esophagus. "In esophageal cancer, activation of P4HA1 by STAT1 transcription could boost cell growth and survival." (PMID 38250070, 2023).
invasive breast carcinoma (3 papers, 2020 to 2021). A carcinoma that infiltrates the breast parenchyma. "We discovered that P4HA1 mutation was associated with the pathological type and mutation count of invasive breast cancer." (PMID 34966739, 2021). "Furthermore, in invasive breast carcinoma, there was a substantial rise in mRNA levels of P4HA1 (FC = 1.219, p = 5.25E-6)." (PMID 33692831, 2021).
pancreatic ductal adenocarcinoma (3 papers, 2020 to 2021). An infiltrating adenocarcinoma that arises from the epithelial cells of the pancreas. "The prolyl 4-hydroxylase subunit alpha 1 (P4HA1) is critically involved in the glycolytic phenotype of pancreatic ductal adenocarcinoma (PDAC) cells, which can be transactivated by HIF-1α under hypoxic condition and further enhances HIF-1α stabilization." (PMID 33436044, 2021). "Recent studies about pancreatic ductal adenocarcinoma revealed that P4HA1-HIF-1α as a crucial regulator involved in glycolysis and oncogenic activities, such as proliferation, chemoresistance, and stemness." (PMID 34659558, 2021).
rectum adenocarcinoma (3 papers, 2020 to 2025). An adenocarcinoma arising from the rectum. "P4HA1 expression was significantly increased in COAD/rectum adenocarcinoma (READ) compared with normal colon tissue." (PMID 41469036, 2025).
thyroid carcinoma (3 papers, 2020 to 2024). "We found that P4HA1–3 proteins were more highly expressed in thyroid carcinoma tissue than in normal thyroid tissues." (PMID 38806556, 2024).
cervical cancer (2 papers, 2021 to 2022). A primary or metastatic malignant neoplasm involving the cervix. "P4HA1 was included in a five-gene signature to predict cervical cancer prognosis." (PMID 35574500, 2022). "The functional study shown that expression of AK4, HK2, P4HA1, TGFBI and VEGFA can regulate the proliferation, migration, and invasion ability of cervical cancer cells." (PMID 34217310, 2021). "The colony formation and transwell assays results showed that reduced AK4, HK2, P4HA1, TGFBI and VEGFA expression, which significantly inhibited proliferation, migration and invasion ability of cervical cancer cells." (PMID 34217310, 2021). "The functional study shown that expression of AK4, HK2, P4HA1, TGFBI and VEGFA can regulate the proliferation, migration, and invasion ability of cervical cancer cells in vitro." (PMID 34217310, 2021). "The results obtained with RT-PCR and immunohistochemistry assays both showed that AK4, HK2, P4HA1, TGFBI and VEGFA were all highly expressed in these cervical cancer tissue samples." (PMID 34217310, 2021). "Moreover, the result of RT-PCR and immunohistochemistry demonstrated that AK4, HK2, P4HA1, TGFBI and VEGFA were all highly expressed in these cervical cancer tissue samples." (PMID 34217310, 2021). "Furthermore, to verify the accuracy of the 5-gene signature, we examined the expression of the signature genes (AK4, HK2, P4HA1, TGFBI and VEGFA) in clinical samples from 10 cervical cancer patients by qPCR and IHC analysis." (PMID 34217310, 2021). "Among them, AK4, P4HA1 and TGFBI were first confirmed as oncogene in cervical cancer." (PMID 34217310, 2021). "Moreover, the results of qPCR and immunohistochemistry staining assay revealed that the expression of AK4, HK2, P4HA1, TGFBI and VEGFA is high in cervical cancer." (PMID 34217310, 2021).
clear cell renal cell carcinoma (2 papers, 2022). "P4HA1 expression was increased in clear cell renal cell carcinoma (RCC) compared to adjacent normal tissues, and P4HA1 positively correlated with the overall survival (OS) and disease-free survival (DFS) in papillary RCC." (PMID 35812752, 2022).
COVID-19 (2 papers, 2021 to 2022). A disease caused by infection with severe acute respiratory syndrome coronavirus 2. "Extracellular proteins which are higher in the COVID-19 group were mainly involved in processes of clot formation (fibrinogens and plasminogens), lipid transport (apolipoproteins) as well as de-novo collagen synthesis (Serpin H1 and prolyl 4-hydroxylase subunit alpha-1)." (PMID 36526981, 2022).
myocardial infarction (2 papers, 2024). Gross necrosis of the myocardium, as a result of interruption of the blood supply to the area, as in coronary thrombosis. "However, the role of P4HA1 in cardiovascular diseases such as myocardial infarction, ischemia-reperfusion, and heart failure with preserved ejection fraction remains to be explored." (PMID 39568592, 2024). "Additionally, SP1 may offer protection against coronary atherosclerosis and cardiac remodeling post-myocardial infarction by influencing the gene transcription of PSRC1, ABCA1, SR-BI, and P4Ha1." (PMID 39062521, 2024).
acute myeloid leukemia (1 paper, 2022). Acute myeloid leukemia (AML) is a group of neoplasms arising from precursor cells committed to the myeloid cell-line differentiation. "P4HA1 expression was increased in diffuse large B-cell lymphoma (DLBCL), brain lower grade glioma (LGG), and uterine carcinosarcoma (UCS) tumor tissues compared to the adjacent normal tissues, whereas it was decreased in acute myeloid leukemia (AML)." (PMID 35812752, 2022).
asthma (1 paper, 2024). "Chelidonium majus relieved OVA-induced asthma in rats by regulating the Alox15, P4ha1, Pla2g16, Pde3a, Nme1, Entpd8 and Adcy9 genes expression to restore the disorders in energy metabolism and inflammation." (PMID 38671520, 2024).
brain tumors (1 paper, 2017). "In vivo studies revealed that the downregulation of P4HA1 inhibited intracranial tumor growth, prolonged the overall survival time of xenograft mice and suppressed the neovascularization in brain tumors." (PMID 28415787, 2017).
cerebrovascular diseases (1 paper, 2024). "We hope that with the continuous advancement of technology and the continuous development of research, the potential of P4HA1 in treating cardiovascular and cerebrovascular diseases will gradually be discovered and realized." (PMID 39568592, 2024).
chondrosarcoma (1 paper, 2019). A malignant cartilaginous matrix-producing mesenchymal neoplasm arising from the bone and soft tissue. "The expression of P4HA1/P4HA2 affected by hypoxia was also reported in chondrosarcoma cells and soft tissue sarcomas." (PMID 31467922, 2019).
Cirrhosis (1 paper, 2022). A chronic disorder of the liver in which liver tissue becomes scarred and is partially replaced by regenerative nodules and fibrotic tissue resulting in loss of liver function. "The reduced hepatic concentration of miR-122 in cirrhosis suggests that its deficiency may de-repress the pro-fibrotic prolyl-4-hydroxylase subunit alpha-1 gene." (PMID 35844554, 2022).
corneal disorder (1 paper, 2026). A non-neoplastic or neoplastic disorder that affects the cornea. "TMEM45A directly binds prolyl-4-hydroxylase (P4HA1) to modulate extracellular matrix (ECM) synthesis, thereby contributing to fibrosis and corneal disorders." (PMID 41959721, 2026).
diabetic (1 paper, 2017). "In addition, alteration of MMPs-9, −13 and −14 expression, PARP-1, HIF1α, and increased collagen biosynthesis as well as collagen cross-linking protein, P4HA1 and PLOD2 were observed along with diminished vascular density in diabetic kidney." (PMID 28883608, 2017).
diabetic cardiomyopathy (1 paper, 2022). Diabetic cardiomyopathy is a disorder of the heart muscle in people with diabetes. "The KEGG results suggested that “HIF-1 signaling pathway,” “diabetic cardiomyopathy,” “lysine degradation,” and so on might be involved in the effect of P4HA1 on tumorigenesis." (PMID 35812752, 2022).
endothelial dysfunction (1 paper, 2024). In vascular diseases, endothelial dysfunction is a systemic pathological state of the endothelium (the inner lining of blood vessels) and can be broadly defined as an imbalance between vasodilating and vasoconstricting substances produced by (or acting on) the endothelium. "Overexpression of P4HA1 enhanced HUVEC proliferation, migration, and tube formation, while its depletion led to endothelial dysfunction." (PMID 38238754, 2024).
fibrosis (1 paper, 2017). the formation of excess fibrous connective tissue in an organ or tissue in a reparative or reactive process. "For example, in vitro and in a mouse fibrosis model miR-122 expression was reduced in activated HSCs supporting their proliferation which appears to be mediated by direct targeting of prolyl 4-hydroxylase subunit alpha-1 (P4HA1)." (PMID 28538690, 2017).
glomerulosclerosis (1 paper, 2016). A hardening of the kidney glomerulus caused by scarring of the blood vessels. "The anomalies in the glomerulus were notable worse in the Wnt5a+/-;P4ha1+/- adult mice being in line with a severe glomerulosclerosis condition." (PMID 26794322, 2016).
idiopathic pulmonary fibrosis (1 paper, 2024). Idiopathic pulmonary fibrosis (IPF) is a nonneoplastic pulmonary disease that is characterized by the formation of scar tissue within the lungs in the absence of any known cause. "However, P4HA1 has not been reported in lung fibrosis, such as idiopathic pulmonary fibrosis." (PMID 39568592, 2024).
leukemia (1 paper, 2021). A malignant (clonal) hematologic disorder, involving hematopoietic stem cells and characterized by the presence of primitive or atypical myeloid or lymphoid cells in the bone marrow and the blood. "Decreased P4HA1 expression was only observed in KICH and LAML (Leukemia)." (PMID 34966739, 2021).
lymph node metastasis (1 paper, 2021). "Also, we found no significant relation in P4HA1 mRNA expression with age, gender, lymph node metastasis and stage." (PMID 34659558, 2021).
metabolic syndrome (1 paper, 2025). A cluster of metabolic risk factors for CARDIOVASCULAR DISEASES and TYPE 2 DIABETES MELLITUS. "Here, it has been demonstrated for the first time that SEMA, a GLP-1RA with known pharmacological effects on metabolic syndrome, is able to reshape PDAC stroma preventing T lymphocyte exclusion by P4HA1-collagen-pCAF axis." (PMID 39828692, 2025). "Moreover, even if P4HA1 has been indicated as a prognostic biomarker of several cancers, at present no dedicated studies have analysed its sensitivity to TME developed upon metabolic syndrome." (PMID 39828692, 2025).
metastatic prostate carcinoma (1 paper, 2014). A carcinoma that arises from the prostate gland and has spread to other anatomic sites. "Gene expression profiling studies and transcriptome sequence analysis showed up-regulation of P4HA1 in metastatic prostate cancer." (PMID 25115393, 2014). "We validated the FLRT3 results across benign, prostrate carcinoma and metastatic prostate cancer tissues by immunoblot analysis which confirmed the inverse correlation between P4HA1 and FLRT3." (PMID 25115393, 2014).
morbid obesity (1 paper, 2023). An excess of body weight, normally defined as an individual with a body mass index greater than 35 or a body weight greater than one hundred percent of ideal body weight. "Furthermore, a study has shown differential expression of P4HA1 in the liver of patients with morbid obesity." (PMID 37697333, 2023).
non-small cell lung carcinoma (1 paper, 2021). A group of at least three distinct histological types of lung cancer, including non-small cell squamous cell carcinoma, adenocarcinoma, and large cell carcinoma. "In this study, we identified that P4HA1 mRNA and protein are both up-regulated in non-small cell lung cancer (NSCLC)." (PMID 34659558, 2021).
osteogenesis imperfecta (1 paper, 2022). Osteogenesis imperfecta (OI) comprises a heterogeneous group of genetic disorders characterized by increased bone fragility, low bone mass, and susceptibility to bone fractures with variable severity. "Additionally, P4HA1 is associated with the collagen-dependent bone disease osteogenesis imperfecta: as P4HA1 is involved in the post-translational modification of collagens, a direct involvement in the pathogenesis of osteogenesis imperfecta is conceivable." (PMID 35269711, 2022).
prostate tumor (1 paper, 2014). "Our studies indicated that in prostate epithelial cells over-expressing P4HA1 either MMP1 knockdown or addition of FN-439 significantly reduced MMP1 mediated prostate tumor cell invasion." (PMID 25115393, 2014). "Our studies indicate P4HA1 copy number gain in a subset of metastatic prostate tumors and its expression is also regulated by microRNA-124." (PMID 25115393, 2014).
renal cell carcinoma (1 paper, 2022). "We also assessed the expression of P4HA1 in renal cell carcinoma (RCC) tissues and confirmed its biological function and latent mechanism via a series of in vitro experiments." (PMID 35812752, 2022). "We also further explored the biological function and mechanism of P4HA1 in renal cell carcinoma (RCC)." (PMID 35812752, 2022).